NEAT1 (nuclear paraspeckle assembly transcript 1)
Diseases named in the same sentence as NEAT1 in open-access papers (continued):
Sharing a sentence is not in itself a finding about the gene and the disease.
glioma (continued). "LncRNA NEAT1 overexpression promotes glioma cell proliferation and glycolysis by stabilizing PGK1." (PMID 37723547, 2023). "NEAT1 overexpression also promotes glioma progression through the stabilization of PGK1." (PMID 37403043, 2023). "In this study, we found that NEAT1 was overexpressed in glioma." (PMID 35123484, 2022). "NEAT1 lncRNA is induced by the EGFR pathway in glioma which then sequesters the chromosome modification enzyme EZH2 to facilitate repression of certain target genes and to promote nuclear translocation of β-catenin, thus activating the WNT/β-catenin oncogenic pathway in GBM." (PMID 36009578, 2022). "Finally, we identified the role of NEAT1 as a potential biomarker and therapeutic target for glioma treatment." (PMID 35123484, 2022). "For example, NEAT1 knockdown inhibits the proliferation of glioma cells both in vitro and in vivo." (PMID 35359381, 2022). "And, NEAT1 levels were characteristically overexpressed in glioma cell lines." (PMID 35123484, 2022). "Thus, here we checked m6A modifications of previously reported glioma associated lncRNAs: MALAT1, NEAT1, XIST1, TUG1, CRNDE, LINC00461, and HOTTIP." (PMID 35361860, 2022). "GBM tissues expressed higher level of NEAT1 than low grade glioma and normal brain tissues." (PMID 35123484, 2022). "NEAT1/PGK1 axis is a candidate therapeutic target for glioma treatment." (PMID 35123484, 2022). "Animal studies were performed to analyze the effect of NEAT1/PGK1 on glioma progression." (PMID 35123484, 2022). "NEAT1 knockdown significantly suppressed the proliferation and glycolysis of glioma cells." (PMID 35123484, 2022). "NEAT1 promoted glioma progression via miR-152-3p/CCT6A and miR-132/SOX2 pathway." (PMID 36523600, 2022). "Collectively, these data suggest that the lncRNA NEAT1 may affect ferroptosis by controlling molecules related to oxidative stress in glioma." (PMID 35912271, 2022). "We analyzed the expression level of NEAT1 in glioma using TCGA and CGGA datasets." (PMID 35123484, 2022). "NEAT1 knockdown significantly suppressed proliferation and glycolysis of glioma cell." (PMID 35123484, 2022). "In human glioma, NEAT1 may, as a ceRNA of miR-194-5p, participate in the anti-angiogenic effect of isoliquiritigenin." (PMID 36213383, 2022). "NEAT1 over expression promotes glioma progression through stabilizing PGK1." (PMID 35123484, 2022). "NEAT1 promotes glioma proliferation and glycolysis through regulating PGK1." (PMID 35123484, 2022). "Taken together, NEAT1/PGK1 axis is indispensable for glioma growth." (PMID 35123484, 2022). "At the same time, NEAT1 is one of the most investigated lncRNAs in glioma." (PMID 35123484, 2022). "Collectively, these results indicated that the NEAT1/miR-128-3p/ITGA5 axis was involved in glioma initiation and progression, and might offer a potential novel strategy for treatment of glioma." (PMID 34263426, 2021). "In addition, knockdown of NEAT1 impedes viability and invasion in glioma cells by suppressing miRNA-132." (PMID 34769497, 2021). "In glioma, NEAT1 has been found to regulate tumor progression via mTOR signaling pathway." (PMID 34263426, 2021). "Tumor xenografts were used to detect the role of NEAT1 in gliomas in vivo." (PMID 33393590, 2021). "Moreover, lncRNA NEAT1 promotes glioma pathogenesis though many of other pathways including NEAT1/miR-449b-5p/c-Met axis, NEAT1/MiR-92b, TLR9/NEAT1/STAT3, NEAT1/microRNA let-7e, miR-152-3p/CCT6A, and miR-139-5p/CDK6." (PMID 33393590, 2021). "NEAT1 demonstrated to be a contributor to glioma cell migration, invasion, and tumor progression." (PMID 34950662, 2021). "The inhibition of lncRNA NEAT1 or BZW1 might be an effective therapeutic strategy to treat glioma cancers." (PMID 33393590, 2021). "Some of previous researches’ work showed that NEAT1 participated in glioma development." (PMID 33393590, 2021).
glioma (continued). "Our results revealed that lncRNA NEAT1 was aberrantly upregulated in GBM cell lines and was directly associated with glioma grades, which was consistent with recent studies, indicating its tumorigenicity in glioma." (PMID 34263426, 2021). "NEAT1 expression was increased in the glioma cells compared with that in the NHA cells." (PMID 33393590, 2021). "The ceRNA effect between NEAT1 and miR-194-5p is related to the angiogenesis of glioma." (PMID 33499813, 2021). "In our study, we observed that NEAT1 was up-regulated in glioma cells." (PMID 33393590, 2021). "We focused on determining which miRNA was affected by NEAT1 in glioma." (PMID 33393590, 2021). "NEAT1 may act as a competing endogenous lncRNA to up-regulate BZW1 by sponging hsa‐mir‐98‐5p in glioma." (PMID 33393590, 2021). "We also identified that BZW1 was positively correlated with NEAT1 in glioma tissues." (PMID 33393590, 2021). "NEAT1 knockdown inhibited glioma cell proliferation in vivo via miR-98-5p/BZW1." (PMID 33393590, 2021). "Particularly, NEAT1 is a pro-oncogenic factor that plays a positive role in various solid tumors, such as liver, prostate, and gastric cancers, as well as renal cell carcinomas and glioma." (PMID 34263426, 2021). "In summary, this may be the first discovery that the NEAT1/ miR-98-5p/BZW1 axis plays an important role in glioma." (PMID 33393590, 2021). "The inhibition of miR-98-5p rescued the knockdown of NEAT1 in glioma cells." (PMID 33393590, 2021). "Taken together, these data suggest that the repression of miR-98-5p could reverse si-NEAT1-induced glioma cell tumorigenesis inhibition." (PMID 33393590, 2021). "LncRNA NEAT1 was up-regulated in glioma tissues compared with that in peritumor tissues." (PMID 33393590, 2021). "However, there are few studies about the role of nuclear-enriched abundant transcript 1 (NEAT1) in glioma." (PMID 33393590, 2021). "The knockdown of NEAT1 resulted in significantly decreased proliferation of the U87 and U251 glioma cells compared with that of cells in the respective control group; the miR-98-5p inhibitor rescued the change in si-NEAT1 expression, resulting in tumor reduction." (PMID 33393590, 2021). "In the present study, we aimed to examine the role of NEAT1 in altering the properties of gliomas." (PMID 33393590, 2021). "In conclusion, NEAT1 is negatively correlated with miR-98-5p in glioma tissues." (PMID 33393590, 2021). "Although NEAT1, miR-128-3p, and ITGA5 have been widely implicated in various tumors, their relationship remains largely unknown in glioma." (PMID 34263426, 2021). "For example, lncRNA NEAT1 was identified as a potential prognostic predictor in glioma." (PMID 32206038, 2020). "LncRNA NEAT1 and linc00152 exerted tumor-promoter role in glioma via modulating ceRNA network." (PMID 32826866, 2020). "Moreover, lncRNA NEAT1's oncogenic activity was enhanced through inverse regulation of miR-449b-5p and c-Met modulation in glioma cells." (PMID 32083078, 2020). "Moreover, NEAT1 was critical for glioma cell growth and invasion by increasing β-catenin nuclear transport and down-regulating ICAT, GSK3B, and Axin2." (PMID 32443824, 2020). "This was the first report on the role and function of lncRNA NEAT1 in glioma." (PMID 32083078, 2020). "NEAT1 facilitated cell migration and invasion in glioma by regulating SOX2 via sponging miR-132." (PMID 32883232, 2020). "Knockdown of NEAT1 suppresses the migration and invasion of glioma cells." (PMID 31243262, 2019). "Furthermore, NEAT1 was upregulated in glioma stem cells, and inhibition of NEAT1 retarded cell proliferation, migration, and invasion." (PMID 30894512, 2019). "We found that lncRNA NEAT1 was significantly decreased by ISL (20 μM) in the U87 glioma cells." (PMID 31438982, 2019). "NEAT1 promoted glioma development by promoting SOX2 expression through suppressing miR-132." (PMID 30053878, 2018).
glioma (continued). "Similarly, the inhibition of NEAT1 via siRNA reduced cancer cell proliferation, migration and invasion in esophageal squamous cell carcinoma, endometrial cancer, glioma, hepatocellular carcinoma and renal cell carcinoma." (PMID 30374364, 2018). "Silencing SOX2 in glioma cells had similar inhibitory effects as NEAT1 knockdown." (PMID 30053878, 2018). "For instance, it was revealed that NEAT1 down-regulation could suppress the development of glioma in vitro through restraining the mobility and viability of glioma cells as well as inducing apoptosis, which was similar to our findings." (PMID 30053878, 2018). "Importantly, NEAT1 was found to be overexpressed in CD133+ glioma stem cells and knockdown of NEAT1 by siRNA reduced the ability of these cells to form colonies in soft agar." (PMID 30374364, 2018). "Knockdown of NEAT1 inhibited glioma cells’ viability, migration and invasion." (PMID 30053878, 2018). "In glioma, NEAT1 mediates the trimethylation of H3K27 in the promoter region of WNT/β-catenin pathway negatively regulated factors (Axin2, ICAT and GSK3B) by physically interacting with the PRC2 subunit EZH2 as a Scaffold, thereby resulting in WNT/β-catenin pathway activation." (PMID 29458374, 2018). "NEAT1 maintains stem-like properties in glioma cells by modulating the miR-107/CDK6 pathway." (PMID 29552296, 2018). "The over-expression of NEAT1 in glioma was also identified by other researchers." (PMID 30053878, 2018). "NEAT1 expression was also elevated in high grade glioma tissues compared with low grade ones." (PMID 30053878, 2018). "NEAT1 knockdown could inhibit the growth and invasiveness of glioma cells through indirectly down-regulating SOX2 by targeting miR-132." (PMID 30053878, 2018). "Knockdown of NEAT1 can suppress glioma stem-like properties via modulating the miR-107/CDK6 pathway, but whether NEAT1 knockdown has the same effect on LSCC needs further investigation." (PMID 29416703, 2018). "In summary, lncRNA NEAT1 was proved to be up-regulated in glioma and targeted miR-132." (PMID 30053878, 2018). "In glioma, NEAT1 could specifically bind to miR-449b-5p and miR-181d-5p to inhibit their transcriptions, leading to the over-expression of oncogenes c-Met and SOX5, respectively." (PMID 30053878, 2018). "In brief, lncRNA NEAT1 was suggested as a tumor promotor in many malignancies, including glioma." (PMID 30053878, 2018). "NEAT1 knockdown in glioma stem cells could restrain cell invasiveness and promote cell apoptosis resulted from the activation of let-7e." (PMID 30053878, 2018). "Clinical analysis could be conducted to evaluate the association between the expression of NEAT1 or SOX2 and the prognosis outcome of glioma patients." (PMID 30053878, 2018). "NEAT1 is overexpressed in CD133+ human glioma primary and CD133+ U87 cells." (PMID 28872613, 2017). "Similarly, increased expression of NEAT1, HOTAIR, and MALAT1 was also found associated with poor prognosis in glioma." (PMID 29138748, 2017). "The lncRNA NEAT1 is required for maintenance of CSCs of glioma." (PMID 28872613, 2017). "Moreover, NEAT1 displays carcinogenicity in multiple types of cancers, such as breast cancer and glioma." (PMID 29147064, 2017). "Likewise, NEAT1 served as a molecular sponge for miR-449b-5p and led to the upregulation of its target c-Met, thus promoting glioma pathogenesis." (PMID 29147064, 2017). "As NEAT1 promoted oncogenesis by downregulating let-7e expression, both of these genes could be considered for application in glioma therapy." (PMID 27556696, 2016). "Herein, we studied the expression and function of NEAT1 in glioma stem cells (GSCs)." (PMID 27556696, 2016). "We thus questioned whether and how glioma cell migration is altered by deletion of the NEAT1 PAS." (PMID 39032650, 2024).
glioma (continued). "NEAT1 (Nuclear Enriched Abundant Transcript 1) is considered as an oncogene in solid tumors such as prostate cancer, hepatocellular carcinoma, gastric cancer, colorectal cancer, and glioma, which promotes the proliferation, metastasis, and drug resistance of tumor cells." (PMID 38006062, 2023). "NEAT1 was reported to function as an oncogene and could promote glioma progression." (PMID 37629061, 2023). "In addition to PTC, the aberrant overexpression of NEAT1 was also observed in other types of cancer, such as glioma, hepatocellular carcinoma, and laryngeal cancer, and the oncogenic effects of NEAT1 on cancer cell proliferation, migration, and invasion were verified." (PMID 35635748, 2022). "However, the effect of NEAT1 on glycolysis of glioma cell and the potential mechanism remain unclear." (PMID 35123484, 2022). "However, little is known about the mechanism of NEAT1 regulating glioma development." (PMID 35123484, 2022). "In addition, NEAT1 expression was positively correlated with PGK1 in glioma." (PMID 35123484, 2022). "Targeting NEAT1/miR-98-5p/BZW1 may be a novel therapeutic treatment approach for glioma patients." (PMID 33393590, 2021). "NEAT1 down-regulation distinguishingly up-regulated the expression of hsa‐mir‐98‐5p and it was demonstrated that hsa‐mir‐98‐5p could reverse the effects of NEAT1 on glioma progression." (PMID 33393590, 2021). "Many lncRNAs could regulate the progression of glioma, like NEAT1, HOTAIR, and GAS5." (PMID 34056009, 2021). "Additionally, NEAT1 was shown to partially mediate TMZ resistance in glioma stem cells." (PMID 34263426, 2021). "This suggested that NEAT1 could function as ceRNAs in glioma." (PMID 33393590, 2021). "In addition, NEAT1/miR-152-3p/chaperonin containing the TCP1 subunit 6A (CCT6A) axis 121 and NEAT1/miR-139-5p/CDK6 axis 122 were shown to inhibit cell apoptosis, while the NEAT1/miR-185-5p/DNA methyltransferase 1 (DNMT1) axis 123 promoted EMT in glioma cells and inhibited cell apoptosis." (PMID 34512157, 2021). "Our data suggest that NEAT1 could promote glioma tumorigenesis via the miR-98-5p/BZW1 axis in vivo." (PMID 33393590, 2021). "Furthermore, NEAT1 and miR-98-5p were validated in NHAs cell line and in two glioma cell lines." (PMID 33393590, 2021). "Importantly, our study identifies a previously unknown ceRNA effect of miR-194-5p and lncRNA NEAT1 between the crosstalk of arachidonic acid (AA) metabolism with angiogenic Akt signaling in glioma." (PMID 31438982, 2019). "Furthermore, ISL downregulated lncRNA NEAT1 but upregulated miR-194-5p in the U87 glioma cell." (PMID 31438982, 2019). "Reprogramming COX-2, mPGES-1 and CYP4A mediated-AA metabolism in glioma by flavonoid ISL inhibits the angiogenic Akt- FGF-2/TGF-β/VEGF signaling through ceRNA effect of miR-194-5p and lncRNA NEAT1, and may serve as a novel therapeutic strategy for human glioma." (PMID 31438982, 2019). "The knockdown of NEAT1 could inhibit glioma cell growth and metastasis." (PMID 30053878, 2018). "Here, we uncovered that NEAT1 could modulate SOX2 expression in glioma by sponging miR-132." (PMID 30053878, 2018). "The aberrant expression of NEAT1 might be a biomarker of the occurrence and exacerbating of glioma." (PMID 30053878, 2018). "It was showed that NRAS may be involved in NEAT1/let-7e-dependent progression of glioma stem cells." (PMID 30583549, 2018). "Further experiments revealed that restoration of let-7e suppresses proliferation and metastasis but promotes apoptosis in NEAT1 knockdown CSCs of glioma, which may be attributable to repression of NRAS, a direct target of let-7e known to induce tumorigenesis and stemness." (PMID 28872613, 2017). "Thus, therapies targeting the NEAT1/let-7e/NRAS axis may be promising options for the treatment of human glioma." (PMID 27556696, 2016).
glioma (continued). "After analyzing the existing literature, we can state that the most reliable data seem to be related to the action of certain lncRNAs in gliomas, such as HOTAIR, NEAT1, MEG3, and MALAT1." (PMID 41149459, 2025). "In the immunosuppressive glioma TIME, Neat1 was upregulated in NK cells but downregulated in immunosuppressive myeloid cells and pro-inflammatory T cells." (PMID 40527978, 2025). "As a component of nuclear paraspeckles, nuclear-enriched abundant transcript 1 (NEAT1) is located on chromosome 11q13.1; this lncRNA is dysregulated in various cancers, like glioma and medulloblastoma." (PMID 39010056, 2024). "Overexpression of NEAT1 stabilizes PGK1 by direct interaction, consequently promoting glycolysis and tumor progression in gliomas." (PMID 39272133, 2024). "To investigate the functional importance of NEAT1 PAS utilization in the production of NEAT1 isoforms in glioma, we utilized CRISPR-Cas9 to delete the NEAT1 PAS (NEAT1 ΔPAS) in the U373 GBM cell line." (PMID 39032650, 2024). "Overall, these findings highlight the NEAT1/miR-324-5p/KCTD20 axis as a novel regulatory pathway and a potential therapeutic target for human glioma." (PMID 38920691, 2024). "Consistent with previous research findings, the other 7 lncRNAs that we have identified in our risk model, have all been reported to play significant biological roles in gliomas, particularly HOXA-AS3, LINC00665, MIR155HG, and NEAT1." (PMID 37403043, 2023). "Neat1 has recently been found to interact with M1 domain of RBP PGK1 and stabilize PGK1, thereby facilitating glioma progression." (PMID 37716986, 2023). "NEAT1 and PGK1 expression levels were positively correlated in glioma tissues, indicating NEAT1 and PGK1 are potential biomarkers for predicting glioma patients prognosis." (PMID 35123484, 2022). "NEAT1 encouraged the activation of HIF1-α and HMGA1, which were both connected to oxidative stress in glioma." (PMID 35912271, 2022). "NEAT1 can elevate the expression of many molecules, including DNMT1, CCT6A, CDK6, SOX2, and c-MET in glioma cells." (PMID 36011001, 2022). "We retrieved 1065 LGG samples from the Cancer Genome Atlas and Chinese Glioma Genome Atlas by machine learning algorithms, identified three hub lncRNAs including CRNDE, LINC00665, and NEAT1, and established an EMT-related lncRNA signature (EMTrLS)." (PMID 36090045, 2022). "SNHG18, NEAT1, LINC00339) and low expression of four lncRNAs (DICER1.AS1, NNT.AS1, WAC.AS1, TTC28.AS1 were with poor prognosis in glioma." (PMID 35237509, 2022). "Knockdown of NEAT1 was able to decrease the expression of BZW1 while up-regulating miR-98-5p, which can inhibit glioma progression in vivo." (PMID 33393590, 2021). "The knockdown of NEAT1 resulted in significantly decreased proliferation of the U87 glioma cells compared with that of cells in the respective control group; the BZW1 overexpression rescued the change in si-NEAT1 expression, resulting in tumor reduction." (PMID 33393590, 2021). "Our studies demonstrated the antioncogenic effects of miR-128-3p, as well as pro-oncogenic impacts of NEAT1 and ITGA5 in glioma cells." (PMID 34263426, 2021). "Although abnormalities of NEAT1, miR-128-3p, or ITGA5 expression have been reported in various studies about glioma, their potential interaction remains a puzzle." (PMID 34263426, 2021). "EGFR is a member of the Erb family of RTKs regulating EGFR/NEAT1/EZH2 axis, and is critical for glioma cell growth and invasion." (PMID 32001707, 2020). "Nuclear enriched abundant transcript 1 (NEAT1), a 4-kb lncRNA, is located in the nucleus and acts as proto-oncogenes in various cancers including glioma." (PMID 33057597, 2020). "Altogether, reprogramming COX-2, mPGES-1 and CYP4A mediated-AA metabolism in glioma by flavonoid ISL inhibits the angiogenic Akt- FGF-2/TGF-β/VEGF signaling through ceRNA effect of miR-194-5p and lncRNA NEAT1." (PMID 31438982, 2019).